IGF1 (insulin like growth factor 1)
Diseases named in the same sentence as IGF1 in open-access papers (continued):
Sharing a sentence is not in itself a finding about the gene and the disease.
Alzheimer disease (continued). "For these reasons, GH and IGF-1 could represent a novel strategy therapy in neurodegenerative diseases such as ALS, Alzheimer’s disease (AD), Parkinson, and dementia." (PMID 29149058, 2017). "Additionally, the relationship was established between the increased IGFBP level and the decreased IGF-1/IGFBP ratio, on the one hand, and the development of Alzheimer's disease (AD) designated sometimes also as the Type 3 diabetes, on the other." (PMID 28031898, 2015). "High-priority targets include established therapeutic genes such as IGF1, for which mecasermin represents an existing FDA-approved treatment, and GRIA1/GRIN2A, which are targeted by memantine and other glutamate receptor modulators currently used in Alzheimer’s disease management." (PMID 41155297, 2025). "However, this mTOR dependent IGF-1/IGFBP5 signaling pathway has not yet been studied in the hippocampus in the context of Alzheimer’s disease and needs further investigation." (PMID 35513854, 2022). "Besides, the therapeutic potential of IGF-1 in diseases characterized by impaired hippocampal function needs to be better investigated, especially considering evidence pointing to brain insulin and IGF-1 resistance in Alzheimer's disease patients." (PMID 25977822, 2015). "Other authors have demonstrated levels of CSF IGF-1 in elderly control subjects of 4.30–4.40 pg/ml, and in elderly cohorts with Alzheimer's disease of 9.44 pg/ml, so it is possible that the ELISA we used was not sufficiently sensitive to detect IGF-1 in this setting." (PMID 25124807, 2014).
Hypertension (152 papers, 2009 to 2026). The presence of chronic increased pressure in the systemic arterial system. "We previously found circulating IGF-1-deficient animals had thinner vascular walls than controls, independently of hypertension." (PMID 38425784, 2024). "IGF-1 deficiency induces functional maladaptation of cerebral arteries to hypertension, partly by the dysregulation of Transient receptor potential (TRP) channel." (PMID 37358957, 2023). "Combined these findings suggest that IGF-1 deficiency is associated with microvascular rarefaction and impaired vascular remodeling in response to stressors such as hypertension." (PMID 36755922, 2023). "Another study found that endocrine IGF-1 deficiency in IGF-1 knockout mice promoted hypertension-induced loss of hippocampal and neocortical microvessel density, which was reversed by IGF-1 infusion." (PMID 37358957, 2023). "IGF-1 deficiency has also been reported to exacerbate hypertension-induced oxidative stress, promote MMP activation, and lead to increased cerebral artery fragility, while antioxidant treatment attenuates age-associated hypertension-induced MMP activation." (PMID 37358957, 2023). "When this model is exposed to hypertension as a cerebrovascular challenge, IGF-1 deficiency increased MMP activation and oxidative stress, increased vessel rigidity, promoted medial atrophy, and decreased vessel elasticity." (PMID 36755922, 2023). "Another study showed that hypertension in IGF-1-deficient mice is associated with impaired adaptive changes in myogenic constriction of cerebral arteries, mimicking the aging phenotype." (PMID 37358957, 2023). "IGF-1 deficiency exacerbates hypertension-induced cerebral microbleeds (CMHs) in mice by Matrix metalloproteinases (MMP) activation, hypertrophy, and structural remodeling in cerebral vessels." (PMID 37358957, 2023). "Using a hypertension-induced model, we confirm that IGF-1 deficient mice exhibited worsened microhemorrhages than controls." (PMID 35356301, 2022). "Both aging and deficiencies in insulin-like growth factor-1 (IGF-1) in the presence of hypertension have been shown to impair upregulation of TRPC within the retina." (PMID 38983558, 2022). "It was recently demonstrated that deficiency of circulating IGF-1 after genetic knock-down of hepatic production of the hormone in mice exacerbates the formation of cerebral microbleeds in response to hypertension, mimicking the ageing phenotype." (PMID 33011936, 2021). "IGF-1 deficiency plays a significant role in promoting hypertension-induced MMP activation, impairing hypertrophy and structural remodeling." (PMID 34881076, 2021). "This microvascular deficiency in hypertension is potentially aggravated by a deficiency in circulating insulin-like growth factor 1 (IGF-1) due to aging." (PMID 33536876, 2020). "Obese and overweight children and adolescents in the higher quartiles of IGF-1 had an increased risk of hypertension, hypercholesterolemia, high levels of triglycerides, and reduced HDL cholesterol." (PMID 32806629, 2020). "The cumulative knowledge gained in a recent meta-analysis supports a direct causality between low IGF1 and hypertension." (PMID 31327319, 2019). "Early studies with focus on patients with congenital or acquired abnormalities in GH/IGF1 production, indicated an association between high IGF1 production and hypertension." (PMID 31327319, 2019). "To study how these changes are related to hypertension, the clinical hallmark of low IGF1, we compared internal correlations between the individual components in normotensive and hypertensive patients." (PMID 31327319, 2019). "Similar to the aging phenotype, in IGF‐1 deficiency, the same level of hypertension leads to significantly increased incidence of CMHs." (PMID 28295976, 2017).
Hypertension (continued). "Our findings suggest that IGF‐1 deficiency itself can exacerbate hypertension‐induced cerebrovascular MMP activation, mimicking the aging phenotype, which likely importantly contribute to the increased fragility of cerebral arteries." (PMID 28295976, 2017). "The IGF‐1‐dependent mechanisms responsible for increased susceptibility of the cerebral circulation to hypertension‐induced injury are likely multifaceted." (PMID 28295976, 2017). "The mechanisms by which IGF‐1 deficiency promote CMHs likely also involve impaired structural and functional adaptation of the cerebral circulation to hypertension." (PMID 28295976, 2017). "To determine the role of IGF‐1 deficiency in the pathogenesis of CMHs, we induced hypertension in mice with liver‐specific knockdown of IGF‐1 (Igf1f/f + TBG‐Cre‐AAV8) and control mice by angiotensin II plus l‐NAME treatment." (PMID 28295976, 2017). "We found that IGF‐1 deficiency impaired hypertension‐induced adaptive media hypertrophy and extracellular matrix remodeling, which together with the increased MMP activation likely also contributes to increased fragility of intracerebral arterioles." (PMID 28295976, 2017). "Collectively, these findings suggest that IGF‐1 deficiency exacerbates hypertension‐induced vascular MMP activation." (PMID 28295976, 2017). "We found that IGF‐1 deficiency exacerbates hypertension‐induced profragility shift in vascular gene expression signature." (PMID 28295976, 2017). "Our findings suggest that IGF‐1 deficiency perturbs arteriolar remodeling processes by impairing hypertension‐induced adaptive media hypertrophy and extracellular matrix remodeling." (PMID 28295976, 2017). "We induced hypertension in IGF‐1‐deficient mice and respective controls (by treatment with angiotensin II [Ang II] and the NO synthesis inhibitor l‐NAME) and compared the incidence, size, and localization of CMHs." (PMID 28295976, 2017). "This cardiomyopathy is due to both a direct action of GH/IGF1 on the heart and to cardiovascular risk factors such as arterial hypertension and glucose intolerance." (PMID 26429918, 2015). "For example, recent studies demonstrate that hypertension in IGF-1 deficient mice is associated with impaired adaptive changes in cerebral arterial myogenic constriction (Toth and Ungvari, unpublished observation, 2012) mimicking the aging phenotype." (PMID 23847531, 2013). "Four hypertension susceptibility genes, IGF1, SLC4A4, WWOX, and SFMBT1, were found by a statistical permutation procedure, confirmed by gene expression analysis, and further replicated using data from the HKHS." (PMID 22479346, 2012). "Moreover, lower IGF-1 is associated with the risk of cardiovascular disease, such as hypertension and vascular dysfunction." (PMID 40538800, 2025). "Increased circulating IGF-1 in plasma reduces the risk of hypertension in women aged 30–55." (PMID 38540997, 2024). "Moreover, some have noted an association between hypertension and insulin resistance and, consequently, with IGF-1, a factor linked to cell growth and the progression of neoplastic conditions." (PMID 39438699, 2024). "For instance, low serum IGF-1 is linked to hypertension and early cardiovascular complications in female patients with rheumatoid arthritis, whereas elevated IGF-1 plasma levels are correlated with a reduced risk for hypertension in non-diabetic women patients." (PMID 39638246, 2024). "IGF-1 deficiency promotes microvascular rarefaction in the hippocampus and the neocortex and leads to structural maladaptation of the cerebral microcirculation to hypertension." (PMID 37358957, 2023). "IGF-1 deficiency also impairs the production and release of vasomediator eicosanoids from astrocytes, alters endothelial nitric oxide (NO) production, and increases susceptibility to hypertension-induced microhemorrhage." (PMID 37358957, 2023).
Hypertension (continued). "In SGA or FGR neonates, hypertension also appears to be associated with exposure to hormone-induced factors of fetal growth restriction, such as elevated levels of insulin-like growth factor-1 (IGF-1), as well as protein restriction in the maternal diet." (PMID 37987283, 2023). "Up to 60% of acromegalic patients are affected by hypertension, caused by different effects (i.e., GH/IGF-1 are anti-natriuretic, the enhancement of the peripheral vascular resistance, and the onset of sleep apnea syndrome) leading to extracellular fluid volume expansion." (PMID 37829686, 2023). "IGF-1 deficiency is associated with obesity and hypertension." (PMID 36770687, 2023). "In addition, a significant association between hypertension and IGF-1 levels was reported in previous studies." (PMID 36407517, 2022). "In addition, single-nucleotide polymorphism analysis of IGF-1 showed that rs35767 is associated with hypertension in Europeans." (PMID 34078313, 2021). "In the presence of excessive salt, individuals with TT genotype with elevated serum IGF-1 level might be susceptible to hypertension and CKD." (PMID 34078313, 2021). "IGF-1 deficiency also impairs the production and release of vasomediator eicosanoids from astrocytes, alters endothelial nitric oxide production, and increases susceptibility to hypertension-induced microhemorrhages." (PMID 34887742, 2021). "In contrast, 87% of IGF‐1‐deficient mice developed signs of hypertension‐induced intracerebral hemorrhage, which occurred within a similar time window (the maximum difference between the cumulative distribution curves for time‐to‐event in the two groups, D, is as follows: 0.2063; P = 0.753)." (PMID 28295976, 2017). "In IGF‐1‐deficient mice, the same level of hypertension led to significantly earlier onset and increased incidence and neurological consequences of CMHs, as compared to control mice, as shown by neurological examination, gait analysis, and histological assessment of CMHs in serial brain sections." (PMID 28295976, 2017). "Additionally, we are just beginning to understand the role of IGF-1 deficiency in hypertension-induced pathology in the vascular system." (PMID 23847531, 2013). "A potential role for IGF-1 on brain VSMCs is highlighted by our previous studies showing that mice with circulating IGF-1 deficiency exhibit pathological cerebrovascular arterial wall ECM remodeling in response to hypertension and impaired cerebrovascular autoregulation." (PMID 38425784, 2024). "This impaired autoregulatory response and ECM remodeling suggests that circulating IGF-1 deficiency leads to maladaptation of VSMCs to hypertension, raising the question of whether VSMCs would exhibit these maladaptive phenotypes if they were unable to receive direct IGF-1 signals." (PMID 38425784, 2024). "However, whether the process of aging additively influences insulin- and IGF-1-mediated endothelial dysfunction and antioxidant deficiency in hypertension and its underlying mechanisms remained unclear." (PMID 34203897, 2021). "This study was designed to test the hypothesis that circulating IGF‐1 deficiency promotes the development of CMHs, by exacerbating hypertension‐induced vascular oxidative stress and MMP activation and/or by impairing microvascular structural adaptation to hypertension." (PMID 28295976, 2017). "GWE was negatively correlated with age (r = −0.41, P = 0.032) and 1.5 × ULN IGF-1 (r = −0.50, P = 0.033) and positively correlated with hypertension history (r = 0.45, P = 0.019)." (PMID 41488995, 2026). "Freeze-dried strawberry powder, rich in polyphenols, has been shown to elevate levels of insulin-like growth factor-1, a bone-forming hormone, in post-menopausal women with pre-hypertension or stage 1 hypertension." (PMID 41601906, 2026). "The importance of IGF-1 in supporting protective microvascular adaptations to hypertension cannot be overstated." (PMID 39271571, 2025).
Hypertension (continued). "In conclusion, preventing CMHs requires a comprehensive approach that includes controlling hypertension and maintaining healthy IGF-1 levels." (PMID 39271571, 2025). "The decline in IGF-1 levels with aging likely plays a significant role in the impaired structural and functional adaptations to hypertension." (PMID 39271571, 2025). "This can activate insulin-like growth factor-1 (IGF-1), which is linked to diseases such as T2DM, cardiovascular disease (CVD), and hypertension (HTN)." (PMID 41194976, 2025). "Understanding the age-related impairments in these adaptive mechanisms highlights the need for therapeutic strategies that enhance IGF-1 signaling to maintain cerebrovascular health and prevent the adverse effects of hypertension in the aging population." (PMID 39271571, 2025). "This review explores the vasoprotective role of IGF-1 signaling in the cerebral microcirculation and its implications for preventing hypertension-induced CMHs in aging." (PMID 39271571, 2025). "Understanding and addressing the decline in IGF-1 signaling with age are crucial for maintaining cerebrovascular health and preventing hypertension-related vascular injuries in the aging population." (PMID 39271571, 2025). "This mini-review discusses the vasoprotective role of IGF-1 signaling in VSMCs and its implications for preventing hypertension-induced CMHs in aging." (PMID 39271571, 2025). "This underscores the importance of maintaining adequate IGF-1 signaling to support cerebrovascular health, particularly in the context of aging and hypertension." (PMID 39271571, 2025). "Despite systemic effects, IGF-1 exerts a wide array of influences in the cardiovascular system affecting metabolic homeostasis, autophagy, hypertension, cardiac contractility and hypertrophy, cardiac fibrosis, and inflammatory." (PMID 39355348, 2024). "Second, low IGF-1 levels reduce nitric oxide production, increase inflammation, and contribute to endothelial dysfunction, leading to heightened vascular resistance, hypertension, atherosclerosis, and a worsened HF prognosis." (PMID 39544311, 2024). "All these data indicate the critical role of the IGF-1/IGF-1R axis in PH development both in the experimental hypertension models and the adult human subjects." (PMID 38540997, 2024). "In summary, we designed a strategy for the induction of IGF1 signaling via the overexpression of the CHIP co-chaperone in stem cells for the treatment of aging hypertension conditions." (PMID 38085649, 2023). "Hypertension causes the suppression of IGF-1 signaling, whereas exercise training elevates IGF-1 levels and promotes the activation of PI3K and Akt signaling." (PMID 37187789, 2023). "Inhibition of the IGF1 signaling pathway by Dox results in cardiotoxicity that manifests as heart failure, myocardial ischemia/infarction, and hypertension." (PMID 36602546, 2023). "IGF-1 prevents myocardial injury and, under hypertension, IGF1 levels were decreased in the cardiomyocytes." (PMID 35890118, 2022). "Fate-mapping approaches, genetic ablation of resident Mφ or specific deletion of IGF1 in resident Mφ recently highlighted that the ability of the heart to adapt to hypertension is dependent on local IGF1 produced by resident Mφ." (PMID 35406812, 2022). "It indicated that the greater decreases in NO production contributed to the worse impairments of endothelium-dependent vasorelaxation mediated by insulin and IGF-1 in the coexistence of aging and hypertension." (PMID 34203897, 2021). "Based on our review of the literature, we proposed that IGF-1 deficiencies reduce vascular density, and induce MVR, that leads to an increase in vascular resistance, hypertension, reductions in CBF, and ultimately cognitive decline." (PMID 33962396, 2021). "The vascular actions of insulin and IGF-1 have been found impaired in some cardiovascular disorders, such as hypertension and obesity." (PMID 34203897, 2021).